PDPK1 (3-phosphoinositide dependent protein kinase 1)
Diseases named in the same sentence as PDPK1 in open-access papers (continued):
Sharing a sentence is not in itself a finding about the gene and the disease.
cancer (48 papers, 2009 to 2025). A tumor composed of atypical neoplastic, often pleomorphic cells that invade other tissues. "PDPK1 has been implicated in treatment resistance and cancer cell growth across several cancer types." (PMID 38542291, 2024). "Further evidence of a specific role for PDK1 in cancer is provided by the observation that increased copy number of PDPK1, the gene encoding for PDK1, is frequently observed in different cancer types." (PMID 31088502, 2019). "Along these lines, recent work has PDPK1 also been implicated in the regulation of self-renewal, cellular transformation, and stemness in several diseases including cancer." (PMID 30064387, 2018). "The findings show that the newly discovered 11-Hydroxytephrosin and Torosaflavone A bind to PDPK1 in an ATP-competitive manner, suggesting that they could one day be used as therapeutic scaffolds against PDPK1-associated diseases including cancer." (PMID 36009858, 2022). "PDPK1-mediated PI3K/Akt signaling is associated with many types of cancers." (PMID 34992655, 2021). "Recently, research demonstrated that PDPK1 is associated with cancer and tumors." (PMID 33384993, 2020). "In doing this analysis, we find that only 95 genes are commonly suppressed by PDPK1 across both cancer contexts." (PMID 38605297, 2024). "Our findings show that 11-Hydroxytephrosin and Torosaflavone A can act as promising inhibitory molecules of PDPK1 and can be used as a starting point for developing effective and selective PDPK1 inhibitors to slow cancer growth." (PMID 36009858, 2022). "So, our study provides novel insights regarding the role PDPK1 plays in cancer pathogenesis and progression." (PMID 35302432, 2022). "PDPK1 is related to signal pathways that are frequently changed in cancer, such as PI3K/Akt, Ras/MAPK, and Myc, as well as with poor prognosis." (PMID 35392240, 2022). "The 3-phosphoinositide-dependent protein kinase 1 (PDPK1) has a significant role in cancer progression and metastasis as well as other inflammatory disorders, and has been proposed as a promising therapeutic target for several malignancies." (PMID 36009858, 2022). "Our method will be valuable in developing cancer therapies that leverage natural leads as powerful PDPK1 inhibitors as well as therapeutic models for metabolic reprogramming." (PMID 36009858, 2022). "PDPK1-mediated activation of the AGC kinase S6K1 connects PDPK1 signaling output with the hedgehog pathway in cancer cells." (PMID 34079928, 2021). "Recently, PDPK1 has also been shown to function as an upstream regulator of the cancer stemness master regulator Myc36." (PMID 34079928, 2021). "The inhibition of PDPK1 activity with antisense RNA or small molecule inhibitors of PDPK1 induces apoptosis or inhibits the proliferation of cancer cells." (PMID 34992655, 2021). "Different from previous studies in human cancer, our data show that PDPK1 knockdown promotes CEF cell proliferation and cell cycle progression after ALV-J infection." (PMID 33384993, 2020). "Considering the important role of PDPK1 20 and VASP 21 in cancer invasion and metastasis, we focused on PDPK1 and VASP for further study." (PMID 32206125, 2020). "Overexpression of PDPK1 promoted cancer migration, invasion, and distant metastasis by regulating AKT phosphorylation 33-34." (PMID 32206125, 2020). "Our data further suggest that combination of PDPK1 inhibitors with docetaxel enhances their anti‐cancer activity, possibly by targeting SGK3‐dependent resistance mechanisms." (PMID 32926495, 2020). "Further analyses revealed that PDPK1 mediates cancer cell survival predominantly via activation of serum/glucocorticoid‐regulated kinase 3 (SGK3)." (PMID 32926495, 2020). "Unexpectedly, and contrary to other cancer types, we observed that PDPK1 gene was under-expressed in PDTC." (PMID 19809427, 2009). "PDPK1 plays a role in cancer-promoting in EOC, and it can be used as a therapeutic target for EOC." (PMID 39624293, 2024).
cancer (continued). "PDPK1 can activate many downstream factors related to the process of diseases, including cancer." (PMID 36820067, 2023). "PDPK1 can activate many downstream effectors and thereby facilitates cancer progression." (PMID 36820067, 2023). "The copy number gain of PDPK1 only showed in the oncocytic cancer cell specimens." (PMID 35392240, 2022). "Overall, our findings suggest that while PDPK1 is regarded as an essential therapeutic target due to its role as a positive regulator of cancer development, proliferation, and migration, natural compounds targeting PDPK1 can be employed to control pathways with anti-cancer effects." (PMID 36009858, 2022). "Consistently, depletion of NOTCH3, NUAK1, or PDPK1 decreased cancer cell migration." (PMID 36072578, 2022). "The coexpression levels of miR-33a-5p and PDPK1 were negatively correlated in cancer tissues." (PMID 34992655, 2021). "Thus, one of the more compelling examinations of PDPK1-governed cancer stemness mediating resistance to chemotherapy emanates from studies in label-retaining cancer cells (LRCCs)." (PMID 34079928, 2021). "By secreting IL-6, macrophages could boost the Warburg effect in cancer cells through IL-6 receptor signaling, inducing the activation of 3-phosphoinositide-dependent protein kinase 1 (PDPK1)." (PMID 34831183, 2021). "Based on these and our results, it is at least questionable whether cancer patients would benefit from a monotherapy with a potent PDPK1 inhibitor molecule and it seems more advisable to target AKT directly." (PMID 33785835, 2021). "PDPK1 is known to phosphorylate AKT that regulates several signalling pathways altered in cancer." (PMID 32926495, 2020). "Among these anti-cancer targets, 3-phosphoinositide-dependent protein kinase-1(PDPK1), MMP1, MMP2, MMP3, nitric oxide synthase (NOS2), and inosine-5′-monophosphate dehydrogenase 2 (IMPDH2) showed similar binding affinity with bruceantin as that of some marketing drugs." (PMID 24429698, 2014). "The 3-phosphoinositide-dependent protein kinase 1 (PDPK1) is the “master kinase of the AGC protein kinase family”, which activates many protein kinase groups including AKT, PKC, and S6K, and encodes a protein of 63,152 Da and plays a crucial role in cancer progression." (PMID 36009858, 2022). "Moreover, because of the crucial role of PDPK1 downstream PI3‐K/Akt pathway in cancer growth and progression 21, 40 and the reported links of this pathway in the regulation of SP1 and DNMT1 expressions in other studies 33, 38, 41, we also assessed the role of Akt signalling in this study." (PMID 28840963, 2018). "Although the study of BRAF and its transcript variants in this cancer type is still in its infancy, we propose that the BRAF‐204 transcript might sustain not only the ERK pathway but also the PI3K/AKT pathway by sponging the oncosuppressive miR‐423 and relieving its targeting of PDPK1." (PMID 40415485, 2025). "PDPK1, for instance, is involved in several signaling pathways, including PI3K/Akt, Ras/MAPK, and Myc, which are frequently altered in cancers." (PMID 37647033, 2023). "The mTORC2 pathway plays a key part of activating Akt, like PDK1(3-phosphoinositide-dependent protein kinase 1) and PI3K, a potential drug target for cancers in which there is Akt deregulation." (PMID 20929525, 2010). "This study highlights the intricate and complex nature of mitotic gene regulation in cancer cells marked by MYC amplification and provides a foundation for future studies to determine the exact mechanism by which N-MYC, WDR5, and PDPK1 converge on cell cycle related processes." (PMID 38605297, 2024). "Considering the pleiotropism of PDPK1 output, it is not surprising that PDPK1 was found to be an essential regulator of cancer stem cell signal transduction." (PMID 34079928, 2021).
cancer (continued). "Unexpectedly, neither a chemical inhibition of PDPK1 with 3 μM compound GSK 2334470 (IC50 ≈ 10 nM) nor a generated cancer cell line with an inducible KD of PDPK1 (> 90% KD) did mimic the phenotype of ERp57 KD." (PMID 33785835, 2021). "Here we discuss the role of PDPK1 as an emerging regulator of cancer stemness by reviewing recent findings in functional CSC models like label-retaining cells (LRCCs), studies in autochthonous animal models of cancer, as well as CSC traits supported by PDPK1." (PMID 34079928, 2021). "For GI cancer, EGFR, PDGFRA, VEGFA, PDPK1, and MCL1, etc. could be validated as drug targets for anti-cancer drugs." (PMID 32523951, 2020). "A more recent study reported that exosomal miR-181c promoted the destruction of the blood-brain barrier by altering actin dynamics through the downregulation of 3-phosphoinositide-dependent protein kinase-1 (PDPK1) and induced brain metastases in cancer patients." (PMID 27929118, 2016). "As a first example, a previous study demonstrated that PI3k/Akt is an important influential factor in cancer, but PDPK1 was not known for its influence in cancer formation." (PMID 25707690, 2015). "However, whether PDPK1 and WDR5 contribute to similar mitotic gene regulation in MYC-overexpressing cancers remains unclear." (PMID 38605297, 2024). "Interestingly, comparison of PDPK1-regulated genes to previous data collected in U2OS cancer cells shows that genes related to spindle pole function and chromosome segregation are conserved genes regulated by PDPK1 regardless of cancer context." (PMID 38605297, 2024). "Taken together, we conclude that PDPK1 predominately contributes to context-dependent gene expression, but regulation of genes related to mitosis may be a conserved function of PDPK1 regardless of cancer cell type." (PMID 38605297, 2024). "Notably, of the eight cancer-related genes, six (TSC1, TSC2, PIK3CA, IGF1R, PDPK1 and AKT2) are known longevity related genes according to GenAge database in human/model organisms, and genetic manipulation of these genes can directly lead to shortening or extending lifespan of model organisms." (PMID 37582720, 2023). "Because of the crucial role of PDPK1 downstream PI3‐K/Akt pathway in cancer growth and progression 21, 40 and the reported links of the Akt in regulation of SP1 and DNMT1 expressions in several cancer types in other studies 33, 38, 41, we then assessed the role of Akt signalling in this process." (PMID 28840963, 2018). "Here, we reveal that pharmacological inhibition of the cytoplasmic activity of 3-phosphoinositide-dependent protein kinase 1 (PDK1) selectively promotes the formation of the core assembly, but not the purinosome, in cancer cells." (PMID 29668719, 2018).
infection (5 papers, 2017 to 2025). The state of being infected such as from the introduction of a foreign agent such as serum, vaccine, antigenic substance or organism. "Additional support for the role of extracellular kinases in VSV-S comes from observation that polyclonal or monoclonal Abs targeting Akt or PDPK1 inhibited VSV-S infection." (PMID 36245045, 2022). "Conversely, the PDPK1 expression in CEF cell was upregulated after ALV-J infection except for 36 h after infection." (PMID 33384993, 2020). "Previously the expression and purification of the T-loop phosphorylated and constitutively active p70S6K1 form have been reported in HEK293 cells via transient transfection and in Sf9 cells through co-infection with two recombinant viruses encoding S6K1 and PDPK1 constructs." (PMID 39821712, 2025). "Silencing of PDPK1, Akt1, or PLCγ resulted in a reduction in VSV-S infection supporting the importance of this signaling pathway." (PMID 36245045, 2022). "Even after controlling for reduced fusion, infection was still significantly diminished by treatment with PKC and PDPK1 inhibitors, indicating that these kinases influence both fusion as well as post-entry stages of infection." (PMID 29970186, 2018). "Altogether, mTORC2 and PDPK1 are the kinases responsible for AKT S473 and T308 phosphorylation, respectively, during infection." (PMID 28953980, 2017). "Previously, we have tested the expression of active S6K1 via co-infection with the PDPK1 carrying virus (data not shown)." (PMID 39821712, 2025). "Furthermore, silencing of PDPK1 prevented VSV-S induced phosphorylation of Akt following VSV-S infection as evidenced by microscopy of non-permeabilized and permeabilized cells." (PMID 36245045, 2022). "To ascertain the kinase responsible for phosphorylation on residue T308 of AKT during infection and its potential relationship with mTORC1 activation, we first infected wild-type and Tbk1-/- cells with WSN in the absence or presence of BX795, an inhibitor of PDPK1, TBK1 and IKKε." (PMID 28953980, 2017). "mTORC1 activation was inhibited in the absence of PDPK1 during infection." (PMID 28953980, 2017). "Anti-ACE2 (murine mAb), anti-Akt (rabbit polyclonal), and anti-PDPK1 (rabbit polyclonal) significantly inhibited VSV-S, but not VSV-G infection." (PMID 36245045, 2022). "Silencing of PDPK1, Akt1 and PLCγ1 resulted in significant reduction of VSV-S but not VSV-G infection." (PMID 36245045, 2022).
PDPK1 also shares sentences with these, for which no sentence is quoted: acute myeloid leukaemia (2 papers); diffuse large B-cell lymphoma (2); non-small cell lung carcinoma (2); Obesity (2); renal cell carcinoma (2); alcoholic steatohepatitis (1); basal cell carcinoma (1); brain cancer (1); cardiac hypertrophy (1); cardiovascular disease (1); Chagas disease (1); Chlamydia infection (1); epilepsy (1); esophageal cancer (1); head and neck carcinoma (1); hemangioendothelioma (1); infarction (1); liver failure (1); lymphoma (1); McArdle disease (1); medulloblastoma (1); metabolic syndrome (1); metastatic tumors (1); ovarian tumor (1); pancreatic adenocarcinoma (1); prostate tumors (1); Rubinstein-Taybi syndrome (1); Sepsis (1); septic shock (1); small cell lung carcinoma (1).
A further 3 diseases each share a sentence with PDPK1 in 1 paper.